SGK1 (serum/glucocorticoid regulated kinase 1)
Diseases named in the same sentence as SGK1 in open-access papers (continued):
Sharing a sentence is not in itself a finding about the gene and the disease.
depression (continued). "In addition, we found emulsifier-treated animals had decreased expression of PCLO and increased expression of SGK1, which are known biomarkers of clinical depression, a disorder often characterized by HPA axis dysregulation." (PMID 35650224, 2022). "Antidepressants increase hippocampal neurogenesis and studies have shown that serum- and glucocorticoid-inducible kinase 1 (SGK1) was related to depression, which is a mediator of the influence of cortisol on neurogenesis and glucocorticoid receptor (GR) function." (PMID 36844911, 2022). "Similarly, another study showed that chronic corticosterone exposure increased the level of phosphorylated SGK1 in a chronic corticosterone-induced mouse model of anxiety/depression." (PMID 34093127, 2021). "The FoxO and mTOR signaling pathways may be involved in the underlying mechanism of the antidepressant effects of ketamine, and Plin4, Sgk1, Klf2 and Dcaf12l1 may be potential biomarkers for depression in N-methyl-D-aspartic acid receptor antagonist treatment." (PMID 31281445, 2019). "Taking into consideration the complex relationships among SGK1, CHD, and depression, we hypothesize that SGK1 may be a co-pathogenic gene underlying the comorbid mechanisms of CHD and depression." (PMID 31632443, 2019). "Furthermore, the expression levels of Plin4, Sgk1 and Klf2 increased in the striatum samples of rat models of depression following administration of ketamine, and the expression of Dcaf12l1 decreased compared with the control group." (PMID 31281445, 2019). "Finally, the review focuses on the antidepressant-like effects of anti-oxidative nutraceuticals in several preclinical model of depression, resulting from the restoration of the physiological expression and/or activity of SGK1, which leads to an increase in neurogenesis." (PMID 32849818, 2020). "Interestingly, the most important molecular interactors as well as the downstream targets of SGK1 and its upstream modulators are involved in various ways in the etiopathogenesis of depression, constituting a clear link between this signaling pathway and the depressive pathogenesis." (PMID 32849818, 2020). "Since BDNF influences neuronal survival, mood, and long-lasting memory formation and intensifies synaptic plasticity with neuro-regenerative effects by weakening the processes of neuronal degeneration, SGK1 may contribute to several BDNF-dependent neuropsychiatric disorders including depression." (PMID 32849818, 2020). "Furthermore, SGK1 participates in the regulation of dendrite growth and long-term memory formation and contributes to the pathophysiology of several neuronal diseases including Parkinson’s disease, Alzheimer’s disease, schizophrenia, and depression." (PMID 31632443, 2019). "SGK1 additionally contributes to the regulation of neuroexcitability, inflammation, and oxidative stress reactions, which may be involved in the pathogenesis of depression." (PMID 31632443, 2019). "The current study indicated that Plin4, Sgk1, Klf2 and Dcaf12l1 were differentially expressed in depression models treated with ketamine, phencyclidine and memantine, which suggested that these genes may be the targets of the NMDA receptor antagonist treatment." (PMID 31281445, 2019). "Therefore, we subsequently examined whether Sgk1 mRNA expression is increased in a mouse model of depression-like symptoms wherein the HPA axis plays an important role." (PMID 21655274, 2011). "Oleanolic acid produced antidepressant‐like effects in mice exposed to chronic stress, while decreased SGK1 and activated BDNF‐AKT/mTOR signaling in the hippocampus in an animal model of CORT‐induced depression." (PMID 37905694, 2024). "UCMS induced anhedonia and hopeless behavior in mice, and changed expression levels of the depression-related genes BDNF, CREB, GR, SGK1, FKBP5, IL-1β, IL-6, and TNF-α in the frontal cortex and hippocampus." (PMID 34358084, 2021).
depression (continued). "The KBD formula normalized UMCS-induced anhedonia and hopeless behaviors in mice by restoring expression of the depression-related genes BDNF, CREB, GR, SGK1, FKBP5, IL-1β, IL-6, and TNF-α in the frontal cortex and hippocampus brain regions." (PMID 34358084, 2021). "Thus, albeit elevated in depression as we hypothesised, SGK1 levels were not linked with glucocorticoid resistance, since they were normal in TRD patients even if they had low GR mRNAs (see also correlation analyses below)." (PMID 32699209, 2020). "Furthermore, there is a linkage between SGK-1 and BDNF, a neurotrophin that has a leading role in the etiology of depression." (PMID 38004136, 2023). "By analyzing levels of sgk1 mRNA, a GRE containing gene, in hippocampal tissue from our animals, we were able to confirm that the GR pathway is active in a nucleus shown to be intimately involved in the manifestation of depression and anxiety." (PMID 33328997, 2020). "Although many genome-wide association studies (GWASs) on depression or CHD have been published, none of these have identified SGK1 as a risk factor." (PMID 31632443, 2019). "Due to the multifaceted pathogenesis of depression, this study aimed to clarify whether the KBD formula ameliorated the effect of UCMS-induced changes in expression levels of the depression-related genes BDNF, CREB, GR, SGK1, FKBP5, IL-1β, IL-6, and TNF-α." (PMID 34358084, 2021). "Furthermore, increased levels of SGK1 were observed in the subgranular zone (SGZ) of the hippocampal dentate gyrus (DG) of miR-17-92 KO mice, which exhibited reduced adult neurogenesis and anxiety- and depression-like behaviors." (PMID 32849818, 2020). "Notably, our results strongly suggested that the reduced serum CORT levels, as well as the restored SGK1, CREB, and BDNF expressions in the frontal cortex and hippocampus, may be involved in the therapeutic action of the ethanol extract of D. alatus leaf in depression." (PMID 31540539, 2019). "Interestingly, SGK1 reported a negative correlation with BDNF, which may evoke a potential mechanism of impaired neurogenesis in depression." (PMID 31540539, 2019).
colon carcinoma (16 papers, 2010 to 2025). "Lower SGK1 levels have been associated with a maturation defect and aggressive behavior in colon carcinoma." (PMID 40613901, 2025). "Following chemical carcinogenesis, SGK1 knockout mice [sgk1(-/-)] mice developed significantly fewer colonic tumors than wild-type littermates [sgk1(+/+)], suggesting that SGK1 deficiency counteracts the development of colonic tumors, an effect due at least in part to upregulation of FOXO3a and BIM." (PMID 33542904, 2020). "In colorectal cancer, SGK1 overexpression promoted colonic tumor cell proliferation and migration and inhibited cell apoptosis induced by 5-fluorouracil (5-FU)." (PMID 33542904, 2020). "In vitro experiments also revealed that SGK1 overexpression enhanced colonic tumor cell proliferation activity and inhibited cell apoptosis induced by 5-fluorouracil (5-FU), while SGK1 shRNA and inhibitors showed inverse effects." (PMID 33542904, 2020). "A previous study showed that Sgk1 (−/−) mice exhibited significantly fewer colonic tumors than Sgk1 (+/+) mice after chemical cancerogenesis, suggesting the therapeutic possibility of SGK1 inhibitors." (PMID 26491696, 2015). "In conclusion, our study shows that only the smallest of the two CpG islands present in the promoter region of SGK1 is methylated in colonic tumour tissues and cell lines." (PMID 21079778, 2010). "Furthermore, SGK1 knockout mice developed fewer colonic tumors than wild-type mice, and inhibiting SGK1 decreased the number of colonic tumors." (PMID 37370761, 2023). "In the same manner, when the mTOR/SGK1 axis is blocked and colon cancer cells are stressing with ROS accumulation, this could induce autophagy to precede apoptosis, so one process depends on each other." (PMID 34123772, 2021). "In addition, similar results were obtained in another report, showing that EMD638683, a selective inhibitor of SGK1, significantly decreased the number of colonic tumors following chemical carcinogenesis in vivo." (PMID 33542904, 2020). "SGK1 has been recently attributed a role in neoplastic transformation, and SGK1 specific inhibitors have been tested in several neoplastic models, including colon carcinoma." (PMID 26462020, 2015). "As hyper-methylation of promoter regions is a well-known mechanism of gene silencing in cancer, we tested whether the SGK1 promoter region was methylated in colonic tumour samples." (PMID 21079778, 2010). "In the original evidence, it was demonstrated that SGK1, through a phosphorylation-dependent positive regulation of SP1, induces a potent and stable transcriptional activity of RANBP1 in colon carcinoma cell lines." (PMID 36672435, 2023). "SGK1 also enhanced the transcript levels RAN-binding protein 1 (RANBP1), a major effector of the GTPase RAN, and decreased Taxol sensitivity in RKO colon carcinoma cells." (PMID 33542904, 2020). "SGK1 also activates transcription of RANBP1, a major regulator of the RAN GTPase, thus affecting mitotic stability and paclitaxel sensitivity in colon carcinoma cells." (PMID 26462020, 2015). "Indeed, a specific inhibitor of SGK-1 activity, SI113, induced cell death in a human colon carcinoma cell line and also potentiated paclitaxel sensitivity." (PMID 35048019, 2021). "Lack of SGK1 blunts the development of spontaneous tumors in APC-deficient mice and chemically-induced colonic tumors in wild-type mice." (PMID 31225494, 2018). "Indeed, a highly selective SGK1 inhibitor, EMD638683, has been shown to suppress colonic tumor growth in vivo." (PMID 26491696, 2015). "We have previously reported down-regulation of the SGK1 transcript in colonic tumour tissue and colorectal cancer cell lines with respect to normal tissue." (PMID 21079778, 2010).
colon carcinoma (continued). "However, SI113-mediated SGK1 inhibition appears to be effective in inducing cell death in RKO cells and potentiating paclitaxel sensitivity, indicating that this new molecule could be efficiently employed, alone or in combination with paclitaxel, in colon cancer chemotherapy." (PMID 33542904, 2020).
colorectal cancer (16 papers, 2010 to 2025). A primary or metastatic malignant neoplasm that affects the colon or rectum. "Our study further demonstrates that GSK-650394 is involved in the generation of pre-metastatic niches in the colorectal cancer livers by inhibiting IR-infiltrating neutrophil SGK1/ERK/NETs signaling, thereby attenuating CRLM progression after IR." (PMID 36788538, 2023). "In colorectal cancer, transfection with a constitutively active SGK1 mutant significantly enhanced cell motility and cell migration via vinculin dephosphorylation." (PMID 33542904, 2020). "Circ0007142-miR-455-5p-SGK1 axis regulates cell proliferation, apoptosis, migration, and invasion of colorectal cancer cells." (PMID 33311443, 2020). "Overexpression of SGK1 in colorectal cancer cell lines resulted differentiation, decreased migration activity, and inhibition of metastasis in an orthotopic xenograft model." (PMID 33542904, 2020). "Reexpression of SGK1 in colorectal cancer cell lines resulted in differentiation, decreased migration rates, and inhibition of metastasis." (PMID 33542904, 2020). "CHKA is known to be over-expressed in human tumours, while SGK1 regulates survival and growth in colorectal cancers." (PMID 29110037, 2018). "We have previously shown that serum/glucocorticoid regulated kinase 1 (SGK1) is down-regulated in colorectal cancers (CRC) with respect to normal tissue." (PMID 21079778, 2010). "We investigated the methylation profile of the two CpG islands present in the promoter region of SGK1 in a panel of 5 colorectal cancer cell lines by sequencing clones of bisulphite-treated DNA samples." (PMID 21079778, 2010). "Development of low molecular weight inhibitors with a high (100-fold) preference for SGK1 as compared to the generically similar kinase Akt and preclinical tests on colorectal cancer supports a synergistic effect of the SGK1 inhibitors with radio- and chemotherapy." (PMID 33777761, 2021). "Moreover, knockdown of SGK1 significantly decreased doxorubicin resistance in colorectal cancer." (PMID 33542904, 2020). "LncRNAs can also modulate T cell differentiation; for example, lnc-SGK1 promotes immunosuppressive Th2/Th17 polarization in gastric cancer, while exosomal CRNDE-h supports Th17 differentiation in colorectal cancer through RORγt." (PMID 41154428, 2025). "To investigate whether down-regulation of the SGK1 transcript could be reversed in colorectal cancer cell lines, we treated the cells with serum and the corticosteroid dexamethasone, both of which have been previously reported to increase transcription of Sgk1." (PMID 21079778, 2010). "Consistent with our findings, a previous study found that the downstream serine/threonine kinase mTOR, which is known to be an important upstream regulator of SGK1 and plays a crucial role in promoting EMT via RhoA and Rac1 signaling in colorectal cancer (CRC)." (PMID 29609629, 2018). "Therefore, Sgk1 could also enhance tumor cell invasion and migration of ESCC, as reported for other human malignancies such as esophagogastric junctional adenocarcinoma, colorectal cancer, and non-small cell lung carcinoma." (PMID 32106831, 2020).
glioblastoma (15 papers, 2015 to 2025). The most malignant astrocytic tumor (WHO grade IV). "Conversely, fewer tumor copy number segments of the SGK1 gene were found to be markedly associated with poor survival in glioblastoma multiforme patients." (PMID 33542904, 2020). "Several studies have shown that SGK1 can increase radiotherapy sensitivity through various means, in multiple cancers, such as lung cancer, glioblastoma, and synovial sarcoma." (PMID 34504628, 2021). "In glioblastoma, the SGK1 kinase inhibitor SI113 drastically reduced cell viability and clonogenic capabilities in vitro and inhibited tumor growth in vivo." (PMID 33542904, 2020). "SI113-mediated SGK1 inhibition markedly induced cytotoxic autophagy in human glioblastoma multiforme cells." (PMID 33542904, 2020). "The observation of SGK1 up-regulation is of particular interest since this kinase has recently been shown to be a key survival kinase for glioblastoma stem cells." (PMID 32946518, 2020). "Furthermore, a lower copy number of the SGK1 gene is associated with poorer survival in glioblastoma multiforme, and an increase in SGK1 favors the survival of patients with glioblastoma multiforme." (PMID 37280474, 2023). "Our results showed that silencing SGK1 could markedly induce autophagy, which was similar to a recent observation that SI113, a SGK1 inhibitor, could dramaticlly trigger autophagy in glioblastoma multiforme (GBM)." (PMID 29609629, 2018). "SGK1 may play a role in glioblastoma resistance to conventional therapies." (PMID 39940838, 2025). "In a follow-up study, the effect of SI113 was also evaluated in glioblastoma multiforme (GBM), one of the most aggressive brain tumors, given that SGK1 overexpression has been documented in GBM." (PMID 36457711, 2022). "Schematic representation of the underlying molecular mechanisms by which leech mediates apoptosis and autophagy through SGK1/Caspase‐3 and PI3K/AKT/mTOR pathways to inhibit glioblastoma." (PMID 41326907, 2025). "Altogether these data establish a link between proteins of the Akt/SGK1/WNK1 signaling module and DDPM cytotoxicity both in quiescent TG1 and TG1-C1 GSC isolated from glioblastoma patients." (PMID 29930759, 2018). "H2S was shown to suppress autophagy via stimulation of SGK1, and inhibition of SGK1 induces LC3 lipidation and BECN1 (member of the PI3KC3 complex) expression in human glioblastoma cells." (PMID 29849891, 2018). "They further showed that SGK1 was overexpressed in highly malignant gliomas and that SI113 dramatically potentiated the effects of radiotherapy, modulated the response to oxidative stress, and induced cytotoxic autophagy in glioblastoma multiforme cells." (PMID 33542904, 2020). "Further, in glioblastomas with activating mutation in EGFR, NF-κB is activated through mTORC2 in an SGK1-dependent manner that does not require Akt or mTORC1, underlying the Akt-independence of this pathway." (PMID 26219339, 2015).
multiple myeloma (14 papers, 2013 to 2026). "For example, increased expression and/or activity of SGK-1 is reported for several human tumors including those involving the breast, tongue, head and neck (e.g., squamous cell carcinoma), ovarian, prostate, multiple myeloma and non-small cell lung cancer." (PMID 37954869, 2023). "In multiple myeloma cell line (MMCL), SGK1 overexpression reduced drug susceptibility to bortezomib that induces endoplasmic reticulum (ER) stress-driven cell death." (PMID 36457711, 2022). "Following genomic analysis revealed that low SGK1 expression was correlated with favorable outcome in multiple myeloma patients treated with bortezomib, indicating that SGK1 promotes tumor growth via raising resistance to ER stress." (PMID 36457711, 2022). "SGK1 is overexpressed in myeloma, medulloblastoma, prostate, colon, ovarian, and non-small cell lung cancer, and induces cell proliferation, survival, and drug resistance." (PMID 33406639, 2021). "In addition, SGK1 (stimulates myeloma cell survival) mRNA levels were downregulated to a similar extent by Dex-Spi and Dex in MM1.S and L-363 cells, again in line with the RNA-sequencing results." (PMID 37578563, 2023). "Increased expression of SGK1 has been shown in myeloma, breast and prostate cancer cell cultures." (PMID 34679726, 2021). "SGK1 is often upregulated in both acute and chronic myelogenous leukemia, such as in myeloma, B-cell lymphoma, and Hodgkin lymphoma, and has been demonstrated to be significantly correlated with enhancer-associated rearrangements and highly recurrent mutations of the SGK1 gene." (PMID 33542904, 2020). "Thus, the overexpression of FGFR1, CCR2, and SGK1 may explain the low sensitivity of multiple myeloma (MM) cells to bortezomib and ixazomib." (PMID 33406639, 2021). "In multiple myeloma, complement C3a activates osteoclasts through the PI3K/PDK1/SGK1 pathway, and the inhibition of SGK1 using EMD638683 significantly reduces osteoclastogenesis, providing a new therapeutic target and strategy for the treatment of multiple myeloma patients." (PMID 40427579, 2025).